CDK9 (cyclin dependent kinase 9)
Diseases named in the same sentence as CDK9 in open-access papers (continued):
Sharing a sentence is not in itself a finding about the gene and the disease.
esophageal adenocarcinoma (4 papers, 2017 to 2023). A malignant tumor with glandular differentiation arising predominantly from Barrett mucosa in the lower third of the esophagus. "Our findings support further exploration of newer CDK9 inhibitors which are more specific and likely to cause lower toxicity with therapeutic doses in patients with esophageal adenocarcinoma compared to the previously used CDK9 inhibitors." (PMID 28404924, 2017). "To evaluate, whether suppression of Axl by CDK9 inhibition is associated with enhanced sensitization to radiation, we stably overexpressed Axl in two esophageal adenocarcinoma cells FLO-1 and SKGT4." (PMID 31384397, 2019). "Lastly, researchers examined the expression of CDK9 in human EAC tissues and Barrett's esophagus and found that CDK9 was overexpressed in EAC." (PMID 33903283, 2021). "We investigated a role of BAY1143572, a new highly specific CDK9 inhibitor, as a sensitizer to radiation in esophageal adenocarcinoma." (PMID 31384397, 2019). "In the present study, we show for the first time that inhibition of CDK9 potently enhances radiation sensitivity in various preclinical models of esophageal adenocarcinoma." (PMID 31384397, 2019). "Previously, we showed overexpression of CDK9 in esophageal adenocarcinoma cells compared to matched normal esophageal epithelial cells and Barrett’s esophagus." (PMID 31384397, 2019). "In conclusion, these findings indicate that targeting CDK9 by BAY1143572 significantly enhances the effects of radiation and Axl is a novel downstream target of CDK9 in esophageal adenocarcinoma." (PMID 31384397, 2019). "Previously, we showed that CDK9 inhibitors exert dose-dependent anti-proliferative effects against 6 esophageal adenocarcinoma cell lines." (PMID 31384397, 2019). "Our findings also indicate that the interplay between CDK9 and Axl should be investigated as a novel mechanism of CDK9 inhibitor mediated radiosensitization in esophageal adenocarcinoma." (PMID 31384397, 2019). "This study provides strong evidence of efficacy of a novel CDK9 inhibitor in preclinical models of esophageal adenocarcinoma, supporting a role of targeted inhibition of CDK9 as sensitizer to the radiation in a clinical trial of esophageal adenocarcinoma." (PMID 31384397, 2019). "Cyclin dependent kinase 9 inhibition is potentially a good therapeutic strategy as CDK9 is diffusely overexpressed in esophageal adenocarcinoma cells as compared to Barrett's esophagus." (PMID 28404924, 2017). "We investigated CDK9 protein expression in EAC and Barrett's esophagus and role of CDK9 in oncogenic processes of EAC in vitro and in murine xenografts." (PMID 28404924, 2017). "The CDK9 expression was significantly higher in invasive adenocarcinoma as compared to CDK9 expression in total (combination of all compartment) Barrett's esophagus and in each compartment of Barrett's esophagus." (PMID 28404924, 2017). "As expected, MCL-1 overexpression led to a reduction of CDK9 inhibitors cytotoxicity in esophageal adenocarcinoma cells." (PMID 28404924, 2017). "The CDK9 expression was significantly higher in EAC as compared to Barrett's esophagus in patient samples." (PMID 28404924, 2017). "All esophageal adenocarcinoma cell lines showed high level of CDK9 protein as compared to a normal esophageal epithelial cell line." (PMID 28404924, 2017). "In this study, we have demonstrated preclinical in vitro and in vivo efficacy of CDK9 inhibition in esophageal adenocarcinoma, by genetic downregulation and pharmaceutical inhibition." (PMID 28404924, 2017). "With limited options of targeted therapy in esophageal adenocarcinoma, exploration of CDK9 inhibitors as therapeutic agents in patients with esophageal adenocarcinoma is warranted." (PMID 28404924, 2017). "Similarity in cytotoxic effects between genetic downregulation and both CDK9 inhibitors support CDK9 as an important therapeutic target in esophageal adenocarcinoma." (PMID 28404924, 2017).
esophageal adenocarcinoma (continued). "The CDK9 expression in lower half of Barrett's esophagus was significantly higher than the upper half." (PMID 28404924, 2017). "In summary, findings in this study demonstrate significant in vitro and in vivo efficacy of CDK9 inhibition in esophageal adenocarcinoma and identify that CDK9 regulates MCL-1 transcription by inhibiting binding of HIF-1alpha to MCL-1 promoter." (PMID 28404924, 2017). "Role of cyclin dependent kinase 9(CDK9) as a potential target in esophageal adenocarcinoma (EAC) is unknown." (PMID 28404924, 2017). "The higher expression of CDK9 in actively proliferating cells also supports use of CDK9 inhibitors in combination with chemotherapy agents as both the agents are likely to be effective in rapidly dividing esophageal adenocarcinoma cells." (PMID 28404924, 2017). "We also studied mechanism of MCL-1 regulation by CDK9 inhibitors in esophageal adenocarcinoma." (PMID 28404924, 2017). "The CDK9 inhibitors used in this study were selected based on their efficacy in other tumors and specificity to CDK9, to study the relevance of CDK9 inhibition in esophageal adenocarcinoma." (PMID 28404924, 2017). "In this study, we compared CDK9 protein expression in matched samples of Barrett's esophagus and invasive carcinoma from patients with esophageal adenocarcinoma and assessed in vitro and in vivo effects of genetic downregulation (shCDK9) and pharmaceutical inhibition of CDK9." (PMID 28404924, 2017). "Thus downregulation of Axl by CDK9 inhibition may be one of the mechanisms by which CDK9 inhibition radiosensitizes esophageal adenocarcinoma cells." (PMID 31384397, 2019). "The CDK9 overexpression is related to the proliferative nature of the cells as higher expression was observed in adenocarcinoma cells and lower half of the crypts (proliferative compartment rich in stem cells) of Barrett's esophagus as compared to upper half of the crypts of Barrett's esophagus." (PMID 28404924, 2017). "Our studies (unpublished data) indicate that CDK9/p-TEFb inhibition is the dominant mechanism of action for three CDK inhibitors: Flavopiridol, CAN 508 and BAY1143572, in esophageal adenocarcinoma." (PMID 31384397, 2019). "Our preclinical data suggest that CDK9 inhibition, particularly by BAY1143572, is a potential strategy for radio-sensitizing esophageal adenocarcinoma and support the investigation of BAY1143572 as an adjunct to radiation in clinical trials." (PMID 31384397, 2019). "These along with no increase in ubiquitin mediated proteosomal degradation by pharmaceutical CDK9 inhibitors, suggest that CDK9 transcriptionally regulates MCL-1 in esophageal adenocarcinoma." (PMID 28404924, 2017). "We further demonstrate that Axl, a tyrosine kinase critical in determining radiation sensitivity in solid tumors, is a novel target of CDK9 inhibitor with and without radiation in esophageal adenocarcinoma." (PMID 31384397, 2019). "Our findings show that MYC is downregulated with shCDK9 in esophageal adenocarcinoma while MYC downregulation by the CDK9 inhibitors is not consistent across three esophageal adenocarcinoma cell lines." (PMID 28404924, 2017). "In contrast, CDK9 expression was observed predominantly in the proliferative zone in the base of the crypt of Barrett's esophagus with minimal to absent staining of the surface epithelium." (PMID 28404924, 2017). "In addition, role of MCL-1 in selecting patients whose tumor is more likely to respond to these CDK9 inhibitors with or without chemotherapy and radiation need to be studied in esophageal adenocarcinoma." (PMID 28404924, 2017). "In both experiments, xenograft tumor growth was significantly inhibited by the CDK9 inhibitors compared to control from day 3 (Flavopiridol) and day 6 (CAN508) to the end of experiment indicating efficacy of both inhibitors in controlling tumor growth in esophageal adenocarcinoma xenografts." (PMID 28404924, 2017).
esophageal adenocarcinoma (continued). "In addition, relevance of CDK9 mediated MCL-1 regulation and mechanism by which CDK9 regulates MCL-1 is not known in esophageal adenocarcinoma, even though CDK9 mediated MCL-1 regulation is one of commonest mechanism by which CDK9 inhibitors have shown anti-tumorogenic effects in other tumors." (PMID 28404924, 2017).
heart failure (4 papers, 2015 to 2022). Inability of the heart to pump blood at an adequate rate to meet tissue metabolic requirements. "As a consequence, constitutive activation of CDK9 leads to mitochondrial dysfunction, which engenders myocyte apoptosis and predisposes the patient to heart failure." (PMID 34146121, 2021). "The undesirable cardiotoxicity caused by CDK9 treatment requires extra vigilance, as the death of patients receiving targeted therapy is not limited to tumor occurrence and metastasis but fatal cardiovascular complications such as severe heart failure and malignant arrhythmia." (PMID 36082129, 2022). "Continuous activation of the Cdk9/Cyclin T1 complex induces not only cardiomyocyte hypertrophy but also cardiac apoptosis by disrupting mitochondrial function, suggesting that the Cdk9/Cyclin T1 complex is a novel target for heart-failure therapy." (PMID 35745840, 2022). "Since CDK9 pharmacological inhibitors dampen hypertrophic signals, modulation of CDK9 activity may thus be a relevant therapy for some kinds of heart failure." (PMID 34146121, 2021).
pancreatic adenocarcinoma (4 papers, 2018 to 2024). "This paradoxical observation is in contrast to another study investigating CDK9 expression in patients with de novo pancreatic adenocarcinoma tumors, which showed that high CDK9 expression has worse clinical outcome as well as its current investigation as a therapeutic target for cancer treatment." (PMID 30405916, 2018). "We filtered drugs through area under the curve (AUC) values that exhibited significant correlations with CDK9 expression in COAD, rectum adenocarcinoma (READ), lung adenocarcinoma (LUAD), lung squamous cell carcinoma (LUSC), and pancreatic adenocarcinoma (PAAD) cancer cell lines." (PMID 39254172, 2024).
periodontitis (4 papers, 2019 to 2022). An acute or chronic inflammatory process that affects the tissues that surround and support the teeth. "To gain insights into the pathologic role of CDK9 in the periodontitis, we first investigated the expression of CDK9, Brd4 and RNA Polymerase II, which coordinate in modulating gene transcription." (PMID 31758083, 2019). "We postulated that by modulating key molecules in the network of cell survival and death, CDK9 plays a pivotal role in the onset and progress of periodontitis." (PMID 31758083, 2019). "Among these, CDK9 has been found to mediate necroptosis in periodontitis." (PMID 35860693, 2022). "In conclusion, our present data demonstrated that butyrate-induced ferroptosis may contribute to the loss of PDLFs during periodontitis development, and the onset of ferroptosis involves p38/HIF-1α activation and BRD4/CDK9 coordination." (PMID 33298848, 2020). "Furthermore, we explored the role of CDK9 in the periodontitis progress by inhibition with FVD or knock-down with shRNA." (PMID 31758083, 2019). "By modulating both the TRIF-dependent alternate and RIPK1-dependent classic necroptosis, CDK9 inhibition may enhance survival of immune cells and reduce release of DAMPs during periodontitis progress." (PMID 31758083, 2019). "Our research demonstrated that CDK9 activation regulated the inflammatory gene transcription and RIPK3-mixed lineage kinase domain-like (MLKL)-mediated necroptosis following P. gingivalis invasion and further influenced the progress of periodontitis." (PMID 31758083, 2019). "In addition, decreased RIPK1 and RIPK3 can be observed in the periodontal tissue in the experimental periodontitis model after FVD treatment, further indicating that CDK9 may modulate necroptosis during periodontitis progression." (PMID 31758083, 2019).
acute lymphoblastic leukemia (3 papers, 2022 to 2025). Leukemia with an acute onset, characterized by the presence of lymphoblasts in the bone marrow and the peripheral blood. "Due to the near perfect conservation of CDK9 and CDK7 between human and mouse, we were able to engineer these mutations in murine B-cell acute lymphoblastic leukemia (B-ALL) cells driven by the BCR-ABL oncogene in a homozygous Arf null background." (PMID 41279360, 2025). "Interestingly, the CDK9 inhibitor and CDK9 degrader have been compared using MOLT4, a cell line derived from acute lymphoblastic leukemia, inducing apoptosis upon administration of both compounds." (PMID 35406461, 2022).
breast tumors (3 papers, 2018 to 2022). "CDK9 also promotes DNA double-strand break (DSB) repair by homologous recombination (HR) by facilitating recruitment of the BRCA1 breast tumor suppressor protein to DNA damage sites and associates with Ku70, which is involved in DSB repair by non-homologous end joining (NHEJ)." (PMID 30405916, 2018). "Our study aimed to determine if CDK9 expression in residual breast tumors following the use of NACT correlated with clinical outcomes." (PMID 30405916, 2018). "CDK9 dysregulation has been described in several human malignancies including tumors of the breast, prostate, and lung origins." (PMID 30647871, 2018). "Given that low CDK9 expression leads to increased spontaneous DNA damage and genetic instability, we speculate that patients with residual breast tumors with low CDK9 expression may have more aggressive disease and thus poorer prognoses." (PMID 30405916, 2018). "One potential benefit of this work is that, with further validation, patients with low CDK9 expression in residual breast tumors following NACT may benefit from more aggressive adjuvant therapies, including enrollment in clinical trials of novel therapies." (PMID 30405916, 2018). "In this study, we evaluated CDK9 expression in post-NACT breast tumors." (PMID 30405916, 2018). "The results of this study do not show a significant relationship between CDK9 expression in residual breast tumors following NACT and improved patient LRR, RFS, and EFS." (PMID 30405916, 2018).
CHARGE-like syndrome (3 papers, 2021 to 2026). "CDK9, cyclin-dependent kinase 9, that regulates transcriptional elongation via RNA polymerase II, has been linked to a neurodevelopmental disorder closely resembling CHARGE-like syndrome." (PMID 41191133, 2025). "In contrast, the CDK9-related CHARGE-like syndrome is an autosomal recessive condition and thus carries a high recurrence risk (25%) for these parents." (PMID 40954203, 2026). "CDK9 has been considered a candidate gene involved in the CHARGE-like syndrome in a pair of cousins." (PMID 33640901, 2021). "However, a causal relationship between CDK9 and the CHARGE-like syndrome was not established." (PMID 33640901, 2021).
COVID-19 (3 papers, 2020 to 2024). A disease caused by infection with severe acute respiratory syndrome coronavirus 2. "Alvocidib is a CDK9 inhibitor with a broad antiviral activity and it has been suggested as a potential candidate for COVID-19 drug repurposing." (PMID 35945222, 2022).
head and neck cancer (3 papers, 2016 to 2022). A primary or metastatic malignant neoplasm affecting the head and neck. "Flavopiridol has previously been demonstrated to be both cytostatic and cytotoxic in prostate, esophageal, lung and head and neck carcinoma cell lines, which has been reported to be mediated through CDK9 inhibition." (PMID 32970704, 2020). "While through a divergent mechanism, our data suggest that CDK9 inhibition may be beneficial for H3K36-mutant head and neck cancers and chondroblastomas, although further research is necessary to test this hypothesis." (PMID 35567477, 2022).
metastatic disease (3 papers, 2020 to 2024). "CDK9’s association with metastatic disease was recapitulated at the protein level in patient samples in which proteomes were profiled using mass spectrometry." (PMID 39117800, 2024). "The mean expression of CDK9 for the metastatic disease group was 2.87." (PMID 31892980, 2020).
prostate tumors (3 papers, 2022 to 2024). "Our data propose that the loss of MRE11 activity should be synthetically lethal with CDK9 inhibitors, and in this context, it becomes important to asses if such losses exist in prostate tumors." (PMID 35164752, 2022). "We further examined CDK9 protein expression by immunohistochemistry (IHC) in castration-sensitive prostate tumors, obtained via transurethral resection of the prostate." (PMID 39117800, 2024).
rhabdoid tumor (3 papers, 2017 to 2024). An aggressive malignant embryonal neoplasm usually occurring during childhood. "In this study, we demonstrate anti-proliferative effects and induction of apoptosis by a combined treatment with BRD4- and CDK9 inhibitors in malignant rhabdoid tumors." (PMID 29156698, 2017).
brain tumor (2 papers, 2022 to 2023). "In addition to AKT, the dephosphorylated kinases included, for example, transcriptional elongation‐promoting kinase CDK9, which is essential for brain tumor‐initiating cells and a synergistic drug target with SMAPs." (PMID 37458534, 2023).
CHARGE syndrome (2 papers, 2021 to 2026). CHARGE syndrome is a multiple congenital anomaly syndrome characterized by the variable combination of multiple anomalies, mainly Coloboma; Choanal atresia/stenosis; Cranial nerve dysfunction; Characteristic ear anomalies (known as the major 4 C's). "For example, a pair of cousins from a single consanguineous family showed CHARGE syndrome-like features, including coloboma, renal malformation, restricted growth, and limb anomalies, but expressed a rare variant of the CDK9 gene, namely p.R225C." (PMID 40954203, 2026). "Before this case, a pair of cousins and three patients with the same homozygous nonsynonymous variant p.Arg225Cys in the CDK9 gene have been reported to exhibit a similar combination of malformations reminiscent of the CHARGE syndrome." (PMID 33640901, 2021). "A pair of cousins from a single consanguineous family has been reported to have CHARGE syndrome-like features including coloboma, renal malformation, restricted growth, and limb anomalies with a rare variant of CDK9." (PMID 33640901, 2021). "Recently, three additional patients from three families with the same homozygous variant, p.Arg225Cys, in CDK9 also were reported to have CHARGE syndrome-like features." (PMID 33640901, 2021). "Notably, the ocular phenotype of retinal dystrophy seen in patients bearing CDK9 variants has yet to be associated with CHARGE syndrome, leading to their diagnosis as having “CHARGE-like malformation syndrome”." (PMID 40954203, 2026). "In addition, three patients with CHARGE syndrome-like features from three different families were homozygous for this same CDK9 variant." (PMID 40954203, 2026). "Previously, we showed that a patient who was compound heterozygous for a different combination of CDK9 variants [p.(A288T/R303C)] did exhibit a multiple malformation syndrome resembling CHARGE syndrome, a classic disorder featuring multiple malformations and caused by CHD7 variant." (PMID 40954203, 2026). "The CHARGE syndrome is an autosomal dominant condition and thus the recurrence risk for the parents will be low when the parents are unaffected, whereas the CDK9-related disorder is an autosomal recessive condition and thus carries a high risk of recurrence of 25% for the parents." (PMID 33640901, 2021). "The phenotypic similarity between the CHARGE syndrome and the CDK9-related disorder is currently unexplainable by molecular interaction between CHD7 and CDK9." (PMID 33640901, 2021).